GOLGA6L26 (golgin A6 family like 26)
Tractability: No criterion of Open Targets' tractability assessment is met for any kind of drug.
Gene: Protein-coding gene on chromosome 15 (23,324,535 to 23,334,196, reverse strand). Ensembl gene ENSG00000273756.
Homologues: Paralogues in human: GOLGA6L1 (99% identical), GOLGA6L6 (95% identical), GOLGA6L22 (94% identical), GOLGA6L25 (93% identical), GOLGA6L24 (93% identical), GOLGA6L2 (47% identical), GOLGA6L7 (43% identical), GOLGA6L4 (22% identical), GOLGA6L10 (21% identical), GOLGA6L9 (19% identical).